GDF15 (growth differentiation factor 15)
Diseases named in the same sentence as GDF15 in open-access papers (continued):
Sharing a sentence is not in itself a finding about the gene and the disease.
type 2 diabetes (85 papers, 2013 to 2026). "On its own, elevated DNAm GDF15 has also been associated with increased risk of incident dementia, type 2 diabetes, and ischemic stroke." (PMID 41274863, 2025). "A prospective cohort study observed that higher baseline levels of GDF-15 in patients with type 2 diabetes were associated with a higher future risk of tumors, including lung cancer." (PMID 40144214, 2025). "The GDF15 EpiScore replicated protein associations with incident dementia, type 2 diabetes and ischaemic stroke in the Generation Scotland test set (hazard ratios (HR) range 1.36–1.41, PFDR < 0.05)." (PMID 39256775, 2024). "This meta-analysis found compelling evidence that elevated circulating GDF-15 level is associated with increased risk for incident MACE including HF in patients with type 2 diabetes." (PMID 35883490, 2022). "We also observed significant associations between GDF15 levels and type 2 diabetes (OR = 1.5, CI = 1.3–1.6, p-value = 2.2 × 10–9)." (PMID 35916366, 2022). "Our results revealed that GDF15 plasma concentration is an independent predictor of all-cause mortality (hazard ratio, HR = 1.7, p-value = 9.2 × 10–12), type 2 diabetes (HR = 1.40, p-value = 0.02), and cardiovascular disease (HR = 1.4, p-value = 1.5 × 10–6)." (PMID 35916366, 2022). "In humans, increasing GDF-15 levels have been associated with inflammation, cardiovascular disease, type 2 diabetes, and cancer." (PMID 33762603, 2021). "In this cohort study, we found a significantly positive association between circulating GDF-15 levels and the risk of DR in individuals with type 2 diabetes." (PMID 33790859, 2021). "In a recent report in patients with type 2 diabetes in Scotland, 205 circulating proteins were evaluated, of which 30 proteins (including GDF-15) were associated with rapid progression of eGFR decline." (PMID 31805809, 2020). "GDF-15 has also been widely studied for its usefulness as a biomarker of cardiovascular events in diabetic patients, and it is interesting to note that GDF-15 was the only biomarker associated with cardiovascular events in patients with type 2 diabetes." (PMID 32899694, 2020). "In db/db type 2 diabetes mice, genetic deletion of GDF15 results in higher level of urinary glucose loss and serum creatinine levels." (PMID 30542297, 2018). "Some studies revealed that circulating levels of GDF-15 in patients with recognized type 2 diabetes were much higher, and GDF-15 is related to increased cancer risk in type 2 diabetes." (PMID 28489602, 2017). "This study suggests that metformin may lower sarcopenia risk, particularly in elderly patients with type 2 diabetes, with GDF15 identified as a promising target for sarcopenia treatment." (PMID 40119457, 2025). "In the Generation Scotland cohort (N ≥ 16,963), GDF15 levels were associated with incident dementia, ischaemic stroke and type 2 diabetes, whereas NT-proBNP levels were associated with incident ischaemic heart disease, ischaemic stroke and type 2 diabetes (all PFDR < 0.05)." (PMID 39256775, 2024). "Using GDF15 and NT-proBNP measures available in Generation Scotland (N ≥ 16,963), we first profile associations between GDF15 and NT-proBNP and four incident diseases (type 2 diabetes, ischaemic heart disease, ischaemic stroke and dementia), in addition to COVID-19 outcome severity." (PMID 39256775, 2024). "Moreover, GDF-15 is associated with a number of circulating proangiogenic endothelial progenitor cells in patients with type 2 diabetes." (PMID 33790859, 2021). "This study establishes the association between DR and GDF-15 in type 2 diabetes." (PMID 33790859, 2021). "In line with a previous study, we also found that the plasma levels of GDF-15 were significantly associated with renal damage and could predict the development of diabetic retinopathy in patients with type 2 diabetes." (PMID 33790859, 2021).
type 2 diabetes (continued). "Moreover, results of our study showed that plasma GDF-15 concentrations were associated with progression of DR in individuals with type 2 diabetes, after controlling for confounding risk factors." (PMID 33790859, 2021). "Renal damage was assessed in GDF15 deficient mouse models of both type 1 and type 2 diabetes." (PMID 30542297, 2018). "In order to investigate whether serum growth differentiation factor 15 is associated with thyroid nodules in type 2 diabetes." (PMID 28489602, 2017). "Regarding the relationship between GDF‐15 and adiponectin, it was recently reported that a high GDF‐15 to adiponectin ratio was independently associated with an increased likelihood of type 2 diabetes in all study groups, and this ratio could be a better indicator of type 2 diabetes." (PMID 41208056, 2025). "Our analysis of GDF-15 distribution across different stages of Type 2 diabetes indicated that GDF-15 levels increase with both the occurrence and progression of the disease." (PMID 41019919, 2025). "GDF15 is significantly increased in overweight and type 2 diabetic patients and correlates positively with serum glucose and HbA1c." (PMID 40820083, 2025). "Studies also report significant associations between elevated GDF‐15 levels and an increased risk of CKD progression, CVD and mortality in individuals with type 2 diabetes." (PMID 40700030, 2025). "Due to this relation of GDF15 with type 2 diabetes, we aimed to calculate specific correlations of glycemic parameters such as random serum glucose concentrations and HbA1c levels with GDF15." (PMID 40820083, 2025). "The findings tentatively suggest that serum GDF-15 increases with the progression of Type 2 diabetes." (PMID 41019919, 2025). "GDF15 is significantly higher in overweight and type 2 diabetic patients and correlates positively with serum glucose and HbA1c." (PMID 40820083, 2025). "Previous research has reported age and sex differences and elevated levels of GDF-15 in obese individuals and those with type-2 diabetes, underscoring the need for caution when extrapolating our findings." (PMID 39902404, 2025). "Since glucose and insulin play an important role in adipocyte differentiation as well as in obese and type 2 diabetic patients, the effect of low glucose vs. high glucose concentrations on GDF15 protein quantity in cell supernatants was investigated by ELISA." (PMID 40820083, 2025). "The most significant association with the GDF-15 level was a trans association with rare variants in JAKMIP1, associated with type 2 diabetes and medications used to treat it82–84." (PMID 38565889, 2024). "Recent studies have extensively explored the potential of GDF-15 as an emerging disease prognosis biomarker in various human conditions such as type 2 diabetes, CVD and cancer clinical outcome and tumor progression." (PMID 38686386, 2024). "Metformin therapy, a type 2 diabetes treatment, has been shown to depend on GDF15 to lower body weight in mice and plasma GDF15 levels increased up to 40% upon metformin therapy in humans." (PMID 35916366, 2022). "Individuals with GDF15 plasma levels above 967 ng/L (the upper quartile) were more than twice as likely to develop type 2 diabetes compared to individuals with lower levels (HR = 2.2, CI = 1.4–3.5, p-value = 7.1 × 10–4)." (PMID 35916366, 2022). "The objective of this study was to evaluate the relationship between circulating GDF-15 levels and diabetic retinopathy (DR) in patients with type 2 diabetes." (PMID 33790859, 2021). "Published data in obese and type 2 diabetic woman show highest GDF15 serum levels in obese patients with type 2 diabetes as compared to lean women." (PMID 33003626, 2020). "In our cross-sectional analysis of individuals with type 2 diabetes from three different cohorts, a multiplex proteomics assay identified four circulating proteins associated with DKD: KIM-1, GDF-15, myoglobin, and MMP-10." (PMID 31805809, 2020).
type 2 diabetes (continued). "In diabetic kidney disease (type 2 diabetes with nephropathy), serum GDF-15 was a promising biomarker of renal functional decline." (PMID 33201838, 2020). "Our findings are in contrast to some reports correlating GDF15 to TG, HbA1c in type 2 diabetes and elderly patients." (PMID 32671100, 2020). "In humans, however, elevated GDF-15 represents a predictor for the future development of type 2 diabetes and, possibly, disease severity." (PMID 32508832, 2020). "Some studies reported that circulating concentrations GDF-15 in patients with type 2 diabetes were much higher, and GDF-15 is related to cell hyperplasia in type 2 diabetes." (PMID 28489602, 2017). "In conclusion, our study suggests that serum GDF-15 is a marker for the development of thyroid nodule in patients with type 2 diabetes over 60 years old." (PMID 28489602, 2017). "In another population with subclinical inflammatory status, both hepcidin and GDF-15 levels were increased and showed a positive correlation in anemic patients with type 2 diabetes." (PMID 27043030, 2016). "Serum GDF-15 levels were increased in obese and type 2 diabetic women and correlated with body mass index (BMI), body fat, glucose, and C-reactive proteins." (PMID 26273671, 2015). "In summary, as GDF15 levels grow, those with Type 2 diabetes are more likely to acquire MS." (PMID 41497484, 2025). "Only two individuals in the full cohort, both within the group with high GDF15, were diagnosed with type 2 diabetes and cancer, thus no analysis of a potential association with these diagnoses was possible." (PMID 40562759, 2025). "Furthermore, GDF-15 expression is markedly increased before the onset of type 2 diabetes, which suggests that GDF-15 is a potential biomarker of DR." (PMID 33790859, 2021). "Altogether, these studies suggest that GDF15 protects from type 2 diabetes." (PMID 34113829, 2021). "Especially in patients with coma or receiving sedation, where the MRC muscle strength score cannot be assessed, the plasma GDF-15 level and the RFcsa loss may diagnose and determine whether patients have ICU-AW at an early stage." (PMID 32104689, 2020). "Moreover, serum GDF15 levels are increased in obese and type 2 diabetic patients and correlated with BMI, body fat, plasma glucose and C-reactive proteins." (PMID 30687235, 2018). "In addition, GDF15 levels are identified as a biomarker for the use of metformin in type 2 diabetes and its concentration reflects the dose of metformin." (PMID 30687235, 2018). "Since GDF-15 has potential cell growth promoting activity and its circulating concentrations in type 2 diabetes are elevated, it is logical to regard GDF-15 as a promising candidate for risk assessment for thyroid nodule in type 2 diabetic patients." (PMID 28489602, 2017). "Our results supported that GDF-15 may be involved in the formation of thyroid nodules in type 2 diabetes." (PMID 28489602, 2017). "Moreover, our work is in line with the previous findings—patients with type 2 diabetes present elevated GDF-15 concentration." (PMID 27043030, 2016). "It has been shown that GDF-15 may be a predictor of several outcomes in type 2 diabetes." (PMID 27043030, 2016). "In individuals with type 2 diabetes, CKD and heart failure, GDF‐15 levels are elevated significantly." (PMID 40700030, 2025). "We therefore applied MR to assess the relationship between genetically determined GDF15 plasma levels and BMI, WHR, glucose, and type 2 diabetes." (PMID 35916366, 2022). "To better evaluate the possible role of GDF-15 in thyroid nodule development in type 2 diabetes, we examined the relationship between serum GDF-15 levels and thyroid nodule in type 2 diabetic patients." (PMID 28489602, 2017). "A recent preclinical study indicated that GDF-15 might also be nephroprotective, as GDF-15 knockout mice showed increased interstitial and tubular damage in models of type 1 and type 2 diabetes." (PMID 41141543, 2025).
type 2 diabetes (continued). "While plasma GDF15 was not altered in patients with Alzheimer's disease in a recent study, it was increased in type 2 diabetes patients with and without comorbid complications." (PMID 36642986, 2023). "Statins do not seem to influence GDF-15 levels, as is observed in diabetes type 2 patients on atorvastatin medication." (PMID 36361969, 2022). "Of note, no transcriptional change of GDF15 mRNA was observed in muscle biopsies from healthy subjects or patients with type 2 diabetes in response to exercise." (PMID 36545337, 2022). "In mouse models of type 1 and type 2 diabetes, damages in renal tubular systems and interstitium, rather than glomerulus, were increased in GDF-15 knock-out mice." (PMID 35204349, 2022). "The mechanism of the microvascular effects of GDF-15 on DR in patients with type 2 diabetes has not been elucidated yet." (PMID 33790859, 2021). "In type 2 diabetes, GDF-15 predicts the development of proteinuria in patients with diabetic nephropathy, suggesting that GDF-15 may be a part of an anti-inflammatory response to microvascular damages." (PMID 33790859, 2021). "We also found significantly higher concentrations of GDF-15 in patients with type 2 diabetes (n = 22) in comparison with non-diabetic patients (median 2694 vs. 1020, respectively, P < 0.001)." (PMID 27043030, 2016). "(2018), a significant increase in serum GDF‐15 levels was observed after a single session of high‐intensity cycling, while in another study, a significant increase in GDF‐15 was reported after 12 weeks of aerobic exercise in obese subjects, which was not similar in subjects with type 2 diabetes." (PMID 41208056, 2025).
Insulin resistance (81 papers, 2014 to 2026). Increased resistance towards insulin, that is, diminished effectiveness of insulin in reducing blood glucose levels. "We have effectively demonstrated a significant association between GDF-15 levels and crucial cardiometabolic risk factors, particularly insulin resistance." (PMID 40722664, 2025). "Elevated GDF15 levels during aging are associated with metabolic dysregulation, including impaired lipid metabolism and insulin resistance." (PMID 40295347, 2025). "Adjusted median regression indicated that male gender (β = 30.1, 95%CI: 11.7, 48.5), older age (β = 9.4, 95%CI: 8.0, 10.7), and insulin resistance (β = 7.73, 95%CI: 1.47, 14.0) indicated a significant positive association with GDF-15." (PMID 40722664, 2025). "Insulin resistance is associated with decreased M2 macrophages, and GDF-15 mediates increased oxidative function in macrophages." (PMID 39781722, 2025). "Although the direct effects of GDF-15 on muscle insulin resistance are not fully understood, elevated GDF-15 levels have been associated with insulin resistance in various tissues, suggesting a potential indirect influence on muscle insulin sensitivity." (PMID 38044678, 2024). "This study aimed to identify the role of GDF-15 and mtDNA deletions as biomarkers of mitochondrial dysfunction, which are suspected to be an underlying contributor to the pathomechanisms of insulin resistance and PCOS." (PMID 39456699, 2024). "Despite this, the association of GDF15 with insulin resistance, dyslipidemia and pro-inflammatory cytokines likely reflects an overall state of metabolic derangement and inflammation in PLWH, known to be related with vascular pathologies." (PMID 35160008, 2022). "Elevated plasma GDF15 is observed in patients with impaired insulin sensitivity and plasma GDF15 concentration is independently associated with insulin resistance measured by HOMA-IR." (PMID 36545337, 2022). "Alterations in FGF21 and GDF15 levels were mainly associated with decreased insulin resistance and increased skeletal muscle mass index, respectively." (PMID 33668309, 2021). "It is now well known that high GDF15 levels are associated with insulin resistance and T2D, and GDF15 has been therefore considered a diagnostic biomarker of T2D." (PMID 33131010, 2021). "Gdf15 deficiency also led to significant insulin resistance in 20‐month‐old mice compared with WT mice." (PMID 32691494, 2020). "Results from another previous cohort study demonstrated that baseline GDF-15 is associated with future insulin resistance and impaired glucose control." (PMID 30350239, 2019). "GDF15 also upregulates the oxidative function of macrophages, leading to polarization into an M2-like phenotype, and reverses insulin resistance in Crif1-deficient mice fed a high-fat diet (HFD)." (PMID 29674655, 2018). "To further characterize the role of macrophage GDF15 in systemic insulin resistance, we performed adoptive transfer of GDF15-deficient macrophages into macrophage-depleted mice." (PMID 29674655, 2018). "The activation of these pathways in the context of GDF15 deficiency and high lipid content may have a strong impact on insulin signaling, thereby contributing to insulin resistance." (PMID 39825925, 2025). "Moreover, our study identifies a significant association between increased GDF-15 concentration and insulin resistance, as indicated by the homeostatic model assessment of insulin resistance (HOMA-IR) and serum insulin levels." (PMID 40722664, 2025). "However, of relevance not only to exercise physiology but also for evaluation of pathophysiological conditions associated with insulin resistance, the endocrine effects of GDF15 need to be unraveled." (PMID 36545337, 2022). "In this study, we demonstrated that Gdf15 deficiency enhanced the infiltration of effector T cells and inflammatory macrophages into the liver and adipose tissues, accentuating liver injury, and insulin resistance in aged mice." (PMID 32691494, 2020).